BRAF (B-Raf proto-oncogene, serine/threonine kinase)
Diseases named in the same sentence as BRAF in open-access papers (continued):
Sharing a sentence is not in itself a finding about the gene and the disease.
melanoma (continued). "Activating BRAF mutations in NSCLC can be categorized into V600 and non-V600, in contrast to the predominance of V600 mutation in melanoma." (PMID 29034207, 2017). "BRAF/MEK inhibitors have profound impacts on the interaction between melanoma cells and the immune system." (PMID 29050218, 2017). "A second patient, a 45-year-old female with a BRAF wild-type melanoma, received nivolumab as neoadjuvant therapy in a clinical trial and became thrombocytopenic (49,000/uL) 43 days later." (PMID 28239462, 2017). "Cobimetinib (Cotellic®; Genentech, San Francisco, California, USA), another MEK inhibitor, appears to have a favorable profile when combined with vemurafenib in patients with advanced BRAF-mutant melanoma." (PMID 29179523, 2017). "Although inhibition of ERK1/2 mostly reduced cell growth of BRAF mutant melanomas, it also showed some partial reduction in NRAS and KRAS mutant cancer cell growth." (PMID 29180761, 2017). "This proof-of-concept study demonstrates the potential of MRI and PAI for detecting the downstream cellular changes induced by Hsp90 and BRAF-MEK-targeted therapies in melanoma cells with potential significance for in vivo imaging." (PMID 28811486, 2017). "Immune and BRAF‐targeted therapies have changed the therapeutic scenario of advanced melanoma, turning the clinical decision‐making a challenging task." (PMID 28463413, 2017). "For example, analysis of five vemurafenib-resistant metastases from a single patient with BRAF-mutant melanoma revealed that MAPK signaling was reactivated in each of the five tumors, albeit through discrete mechanisms." (PMID 28431544, 2017). "This would argue against the role of the BRAF/MEK/ERK pathway in promoting CD47 expression in melanoma cells." (PMID 29050218, 2017). "Multiple studies have reported increased intratumoral T cells infiltration in BRAF mutant melanoma tumors treated with MAPK pathway inhibitors." (PMID 29156850, 2017). "We applied microfluidic single-cell RNA-seq to measure the transcriptome of 92 single cells obtained from a BRAF/NRAS wild type melanoma short-term culture (Ma-Mel-123)." (PMID 27903987, 2017). "B-cell-derived IGF-1 is critical for resistance of melanomas to BRAF and MEK inhibitors due to emergence of heterogeneous subpopulations and activation of FGFR-3." (PMID 28928360, 2017). "For instance, in a study of melanoma patients who received BRAF inhibitors, low concentration of plasma BRAFV600E was significantly associated with longer OS and PFS." (PMID 28061461, 2017). "The first drug combination for treatment of advanced melanoma was approved in January 2014 and involved the BRAF inhibitor, dabrafenib, and the MEK inhibitor trametinib." (PMID 28085880, 2017). "This suggests that melanoma cells have selected through clonal evolution for an optimal level of MAPK signaling, and that the additive effects of a MEK mutation and a BRAF mutation are counterproductive." (PMID 28263969, 2017). "We have applied and validated our method on a high-throughput drug screen of 780 combinations involving 40 individual molecules in the context of mutant BRAF melanoma." (PMID 28085880, 2017). "To better understand the chromosomal mechanisms leading to M%NRAS increase, we compared M%NRAS and NRAS/chromosome 1 copy number status between 32 BRAF/NRAS WT and 57 NRAS Q61 mutated melanomas." (PMID 28668077, 2017). "Here we show that BRAFi induces upregulation of MerTK, a master regulator of phagocytosis, which contributes to acquired resistance to BRAF inhibition in BRAFV600E melanoma." (PMID 29050198, 2017). "Here, we investigated the involvement of PTTG1 in melanoma cell proliferation, invasiveness and response to the BRAF inhibitor (BRAFi) dabrafenib." (PMID 29371923, 2017). "TERT promoter mutations are common in various cancers and found in up to 70% of melanomas, including half of BRAF wild-type cases." (PMID 29108273, 2017).
melanoma (continued). "AMPK phosphorylation and its subsequent activation upon BRAF inhibitor treatment has previously been described in melanoma and colorectal cancer cells." (PMID 28595656, 2017). "Treatment of melanoma with immune checkpoint inhibitors has a lower response rate compared to treatment with BRAF/MEK inhibitors, but the response tends to be more durable, lasting for years." (PMID 28724377, 2017). "We used the same system/vectors from Dr. Zhang's group, which have been used in a human melanoma cell line to screen for genes that are involved in resistance to BRAF inhibitor treatment." (PMID 27086916, 2017). "While combination therapy with BRAF–MEK inhibitors delays melanoma progression and improves overall survival as compared to monotherapy, development of multi-drug resistance still leads to disease relapse in many patients." (PMID 29209327, 2017). "In an in vivo model of BRAFV600E‐mutant melanoma, the combination of BRAF inhibition with either MEK1 or MEK2 knockdown resulted in a modest reduction in metastasis." (PMID 28097822, 2017). "Therapy-induced overexpression of MerTK on the plasma membrane was dependent of the time-course and occurred after 48 hours of BRAFi-treatment in 50% (8 out of 16) of the examined BRAF mutant human melanoma cell lines." (PMID 29050198, 2017). "Melanomas (skin) are indeed an outlier, as both BRAF and NRAS-mutant cells are particularly sensitive to all forms of MAPK inhibition." (PMID 28649441, 2017). "This indicated that BRAF was dispensable after melanoma initiation for tumour growth and maintenance." (PMID 28497782, 2017). "Treatment of BRAF‐mutant melanomas with MAP kinase pathway inhibitors is paradigmatic of the promise of precision cancer therapy but also highlights problems with drug resistance that limit patient benefit." (PMID 28069687, 2017). "For melanomas with NF1 loss‐of‐function mutations or deletions, studies have shown that NF1 ablation can be linked to decreased sensitivity and resistance to BRAF inhibitors both in vitro and in vivo." (PMID 28267273, 2017). "The melanoma cells included BRAF or NRAS mutated cell lines and tumor samples from melanoma patients that have relapsed from current treatments." (PMID 27086916, 2017). "In vitro, 4OHT-induced recombination was highly efficient in double Braff/f;Craff/f melanoma cell culture since BRAF and CRAF expression was nearly undetectable on day 4 and completely abolished on day 7 of treatment." (PMID 28497782, 2017). "Various studies have since shown the utility of testing mutant BRAF in plasma of melanoma patients using ddPCR." (PMID 29108273, 2017). "Currently, the treatment of advanced malignant melanoma made use of immuno-therapy with PD-1 and CTLA-4 inhibitors and, for melanomas harboring BRAF mutation, also, of target therapy with BRAF and MEK inhibitors." (PMID 29100280, 2017). "More recently, we demonstrated that in BRAF-mutant melanoma cells BRAF inhibitor treatment had a similar effect." (PMID 28596940, 2017). "We performed cytotoxicity and apoptosis assays, and a xenograft mouse model to determine the in vitro and in vivo efficacy of JQ1 in combination with Vemurafenib against BRAF‐mutant melanoma cell lines." (PMID 27169980, 2016). "In recent years, there have been improvements in melanoma therapy with the emergence of BRAF-MEK inhibitors and immunotherapy." (PMID 27399772, 2016). "The anti-tumor effect achieved with BRAF-i or MEK-i is primarily exerted on melanoma cells, resulting in marked shrinkage of tumor lesions consequent to apoptotic cell death." (PMID 27563819, 2016). "Activating mutations in the serine/threonine kinase BRAF and in particular BRAFV600E/D mutations occur in about 50% of melanomas." (PMID 26828592, 2016). "A concomitant AURKA/BRAF and AURKA/MEK targeting overcame MAPK signaling activation-associated resistance signature in BRAF- and NRAS-mutated melanomas, respectively, and elicited heightened anti-proliferative activity and apoptotic cell death." (PMID 26962685, 2016).
melanoma (continued). "One of the key oncogenic signaling pathways in melanoma is MEK/ERK, with BRAF, the upstream regulator, constitutively activated in 66% of malignant melanomas." (PMID 26927180, 2016). "Identification of BRAF as an actionable target in advanced malignant melanoma (MM) has led to a dramatic change in the treatment scope of this disease." (PMID 27255157, 2016). "Based on these preclinical data, a clinical trial has been commenced to compare the efficacy of intermittent dosing and continuous dosing with a B-RAF inhibitor and a MEK inhibitor in patients with BRAF-mutant melanoma." (PMID 27270313, 2016). "The pharmacological effects of BRAF and MEK inhibitors were similar between PDX-derived histocultures and their corresponding PDX, on 2 models of BRAF and NRAS-mutated melanomas." (PMID 26909610, 2016). "Binimetinib has also shown similar clinical efficacy in BRAF-mutant melanoma in a phase II study, as well as evidence of activity in NRAS mutated disease." (PMID 26784231, 2016). "In BRAF mutant melanoma cell lines, A375 and SKMEL28, vemurafenib induced a dose-dependent increase in routine respiration and maximum respiratory capacity, two fundamental parameters of mitochondrial function, within six hours of exposure." (PMID 27250023, 2016). "MEK inhibitor and/or BRAF inhibitor additively or synergistically combined with digitoxin to induce cell death, inhibiting growth of patient-derived melanomas in NSG mice and synergistically extending survival." (PMID 27545456, 2016). "Silencing BRAF in these melanomas inhibited MAPK pathway activation, which is illustrated by the reduction of ERK phosphorylation, so we tested the involvement of BRAF protein in melanoma-expressed CD70 using a BRAF specific siRNA." (PMID 26828592, 2016). "Melanoma cells are exquisitely dependent on hyper‐activation of the MAPK‐signaling pathway, with activating mutations in BRAF (around 50%) or other pathway members as key drivers of tumorigenesis." (PMID 27169980, 2016). "Our findings demonstrated that fisetin inhibits melanoma cell invasion, EMT progression and metastasis of BRAF-mutated melanoma cells by modulating the expression of EMT marker proteins and reducing transcription factors related to EMT." (PMID 26517521, 2016). "For example, multiple metastases are induced by the VEGFR kinase inhibitor sunitinib/SU11248 or VEGFR-specific antibodies, and the BRAF inhibitor PLX4720 induces metastasis in RAS- or BRAF-mutant melanoma." (PMID 27556697, 2016). "TRAIL-induced MCL-1 inhibition leads to BIM-mediated apoptosis and low levels of BIM contribute to melanoma's resistance to BRAF inhibitors." (PMID 27829238, 2016). "Vemurafenib and dabrafenib were the first selective BRAF inhibitors (BRAFi) approved for clinical use in 2011 and 2013, respectively, and have clinical response rates of about 50% in BRAF-mutant melanoma." (PMID 27028853, 2016). "BRAF and NRAS mutations are the most common genetic drivers of melanoma, found in ~50% and ~20% of tumors respectively, and are nearly mutually exclusive." (PMID 27152946, 2016). "The key feature of ‘invasive’ melanoma cells is their altered cell attachment and migration phenotype, phenotypes that we found to be also exhibited by BRAF inhibitor-resistant cells." (PMID 27648299, 2016). "As expected, all the BRAF wt melanoma cell cultures were strongly resistant to PLX4720, but some of them also showed strong resistance to the MEK1/2 or to the PI3K/mTOR inhibitors." (PMID 26678033, 2016). "There is an additional need for novel therapies and approaches to the treatment of BRAF wild-type melanomas including NRAS mutant melanoma." (PMID 27447557, 2016). "These pre-clinical results support further evaluation of combination treatment with ixazomib and IFN-α for the treatment of advanced BRAF V600E mutant melanoma." (PMID 27783987, 2016).
melanoma (continued). "Consistent with this, murine cells derived from a genetically engineered mouse model of melanoma driven by mutant BRAF-V600E and PTEN deletion were sensitive to SCH984 (IC50 0.15 μM; Amax: −73.6%)." (PMID 27655717, 2016). "These spindled and proliferative resistant melanoma cells are often found to be derived from short-term adapted, persisted cells that survived the stress of BRAF inhibition." (PMID 27648299, 2016). "In BRAF inhibitor-naive melanoma, JUN has been reported as a regulator of tumor progression and as a potential therapeutic target." (PMID 27648299, 2016). "Further, the OxPhos inhibitor abrogated the growth of inhibitor-resistant BRAF mutant human melanoma cell lines in vivo." (PMID 27461275, 2016). "This concurrent pathway activation was reported in other studies identifying BRAF inhibitor resistance mechanisms in melanoma, where enhanced signaling through the PI3K/AKT pathway is often observed in addition to adaptive reactivation of the MAPK pathway." (PMID 27127178, 2016). "Further study is required to determine the role of RASA1 in melanomas with oncogenic NRAS mutations, especially in metastasis, and the effect of RASA1 on R-Ras activation in melanomas that are wild-type for BRAF and NRAS." (PMID 26993606, 2016). "Melanomas treated with agents that target oncogenic BRAF undergo a reversal of the Warburg effect and become dependent on oxidative phosphorylation." (PMID 26907172, 2016). "MiR-146a (another miR-146 family member) was highly up-regulated by oncogenic BRAF and NRAS mutations in melanomas." (PMID 26646588, 2016). "The same relationship likely applies to melanoma cell lines as well, since most of these tumors harbor activating mutations in the RAS-MAPK pathway, including BRAF V600E and NRAS Q61L/R, as well as the loss of NF1 in a subset of cases." (PMID 27130733, 2016). "Likewise, although double-mutated NRAS/BRAF melanoma cultures have been previously reported, these may still represent heterogeneous mixtures of singly-mutated melanoma cells, or may have arisen artificially through in vitro drug treatment and selection experiments." (PMID 27791198, 2016). "In melanoma, a network of miRs, including miR-211 and miR-222 has been shown to mediate some effects of oncogenic BRAF signalling." (PMID 27852308, 2016). "The poor responses in the bone are consistent with our recent findings that stiff microenvironments rich in matricellular molecules enable BRAF‐mutant melanoma to tolerate BRAF inhibition." (PMID 26414886, 2016). "Sixty-percent of melanomas express a constitutively active form of BRAF (BRAFCA), that is inhibited by BRAFCA-specific inhibitors (BIs)." (PMID 26808375, 2016). "NRAS mutant melanoma cells treated with vemurafenib exhibit a paradoxical activation of the MAPK pathway due to CRAF/BRAF dimerisation and CRAF transactivation." (PMID 27447557, 2016). "Rap1 was shown to form a complex with the mutated BRAF, suppressing the activation of Ras‐MAP kinase signaling and leading to apoptosis in malignant melanoma." (PMID 27339860, 2016). "AXL is also an important factor driving resistance to MAPK inhibitors in BRAF (V600) mutant melanoma." (PMID 27834845, 2016). "Stromal cells, such as lung fibroblast, reduced melanoma sensitivity to BRAF inhibition through proximity-dependent interactions." (PMID 26918352, 2016). "Patients with BRAFV600E mutant metastatic melanoma were also associated with a significantly younger age (median= 57.0 years) compared to patients with BRAF wild-type melanoma (median= 67.0, P= 2.5 × 10−7, Mann-Whitney test)." (PMID 27191502, 2016). "Oncogene-targeted therapies based on mutated BRAF- and/or MEK-specific inhibitors have been developed for melanoma treatment." (PMID 27563819, 2016). "We sought to analyze the influence of BRAF status on LC of melanoma brain metastases (MBM) following Gamma Knife radiosurgery (GK)." (PMID 27200295, 2016).
melanoma (continued). "Whole genome sequencing analyses revealed that Tert promoter mutations are the most frequent mutations after BRAF and NRAS genes in melanomas." (PMID 26846696, 2016). "We first determined the amount of melanin required to inhibit BRAF amplification in the 1676 melanoma cell line." (PMID 27466810, 2016). "The A375 (BRAF V600E mutant) human melanoma tumor cell line was used and cells were plated at a density of 3 × 104 cells/well in a 96 well plate." (PMID 27783987, 2016). "Taken together, these results indicated that intrinsic resistance to BRAFV600E inhibition can be frequently associated with cross-resistance to MEK1/2 and/or PI3K/mTOR inhibitors in BRAF-mutant melanoma cells." (PMID 26678033, 2016). "For example, melanoma cells display enhanced activation of PI3K signaling after treatment with BRAF inhibitor, resulting in tumor cell resistance to the drug challenges." (PMID 26848623, 2016). "In this study, we assessed the effect of combining the BRAF inhibitor Vemurafenib with the BET inhibitor JQ1 in in vitro and in vivo models of BRAF‐mutant melanoma." (PMID 27169980, 2016). "Amblyomin-X sensitive human melanoma cells have mutant BRAF gene that increases kinase activity of BRAF, leading to constitutive activation of the RAS-RAF-MEK-ERK pathway and thus uncontrolled tumor proliferation." (PMID 27015684, 2016). "We have reported that BRAF mutant melanoma cells develop drug resistance when grown in the presence of BRAF inhibitors." (PMID 26365896, 2016). "Supporting this, vemurafenib, which is identical to PLX-4720 except for small modification for pharmacokinetic reasons, was the first BRAF inhibitor approved for the treatment of melanoma patients." (PMID 27654937, 2016). "The discovery of activating BRAF mutations in approximately 50% of melanomas has led to the development of MAPK pathway inhibitors, which have transformed melanoma therapy." (PMID 27655717, 2016). "The MEK inhibitors trametinib can also improve survival in melanoma when used in combination with BRAF inhibitors." (PMID 27582542, 2016). "To analyze the consequences of this upregulation, we isolated A375-GFP melanoma cells from tumor-bearing mice treated with the BRAF inhibitor vemurafenib (100 mg/kg) for 12 days, at which point the tumor response was reaching a plateau." (PMID 26977879, 2016). "At the mechanistic level, BRAF inhibition in BRAFV600E-melanoma cells induced ER-stress and the predominant activation of the PERK–eIF2α–ATF4/ATF3 pathway, which in turn promoted cytoprotective autophagy." (PMID 27896217, 2016). "Recently, a case of a keratoacanthoma (KA) which developed during treatment with Vemurafenib in a BRAF V600E positive melanoma patient was tested positive for the presence of HPyV6 with pronounced viral load." (PMID 27388771, 2016). "Although we do not know the concentration we achieve in mice at 25 mg/kg/day, the levels reached in patients are in the range of the concentration we used (5–10 μM) to sensitize melanoma cells to BRAF or MEK inhibitor-induced cell death in vitro." (PMID 26977879, 2016). "For example, whereas 70% of BRAF mutant melanomas respond to MAPK pathway inhibitors, a substantial subset is intrinsically resistant." (PMID 27655717, 2016). "These patients consisted of progressing (acquired resistant) and matched pre-treatment melanoma tumor samples treated with combined dabrafenib (BRAF inhibitor) and trametinib (MEK inhibitor)." (PMID 27377892, 2016). "Having shown that RASA1 regulates R-Ras activity and that R-Ras regulates Ral-A activity in BRAF mutant melanoma, we next addressed if Ral-A activity was stimulated or suppressed by RASA1 knockdown or overexpression, respectively." (PMID 26993606, 2016). "Changes in melanocytic lesions were seen in patients with advanced melanoma during treatment with BRAF inhibitors." (PMID 27042173, 2016).